ANGPTL3 (angiopoietin like 3)
Diseases named in the same sentence as ANGPTL3 in open-access papers (continued):
Sharing a sentence is not in itself a finding about the gene and the disease.
glomerulosclerosis (4 papers, 2019 to 2024). A hardening of the kidney glomerulus caused by scarring of the blood vessels. "Angptl3 knockout ameliorated glomerulosclerosis by attenuating podocyte loss via rescuing podocytes detachment and apoptosis." (PMID 31126248, 2019). "Angptl3 knockout effectively delayed glomerulosclerosis formation by attenuating podocyte loss through rescuing podocytes from detachment and apoptosis." (PMID 31126248, 2019). "The current study re-evaluated the renoprotective effect of Angptl3 knockout in chronic ADR nephropathy and attempted to explore the mechanism underlying the effect associated with Angptl3 knockout in glomerulosclerosis." (PMID 31126248, 2019). "Our previous studies demonstrated that Angptl3 knockout effectively delayed the formation of glomerulosclerosis by reducing podocyte detachment and apoptosis." (PMID 37638046, 2023). "Our previous work revealed increased Angptl3 expression in the glomeruli of children with nephrotic syndrome (including minimal change disease and glomerulosclerosis) and animal models of Adriamycin (ADR) nephropathy, and in ADR- or puromycin aminonucleoside (PAN)- treated cultured podocytes." (PMID 31126248, 2019). "In the end stage, Angptl3 knockout effectively delayed glomerulosclerosis formation." (PMID 31126248, 2019). "The ANGPTL3 might regulate lipid metabolism, and abnormal regulation of lipid metabolism may involve the glomerular sclerosis earlier, which may induce oxidative stress in local environment under high-fat diet." (PMID 31103046, 2019). "Hence, Angptl3 knockout’s ability to ameliorate podocyte injury and glomerulosclerosis in DN may be partially due to its anti-inflammatory action." (PMID 37638046, 2023). "Furthermore, Angptl3 knockout reduced the numbers of the detached and apoptotic cells in the renal tissue and alleviated podocyte loss in mice with ADR chronic nephropathy, thereby, delaying the glomerulosclerosis formation." (PMID 31126248, 2019).
Hypocholesterolemia (4 papers, 2018 to 2024). An decreased concentration of cholesterol in the blood. "Interestingly, LIPC gene mutation is the second most common cause of familial hypocholesterolemia, after only angiopoietin-like 3 (ANGPTL3), suggesting that LIPC is a promising target for the diagnosis of familial hypocholesterolemia." (PMID 38195542, 2024). "Zebrafish with downregulation of ANGPTL3 expression showed the hypocholesterolemia phenotype." (PMID 36293338, 2022). "For the cases with hypocholesterolemia phenotype, we studied five genes (APOB, PCSK9, MTTP, SAR1B, and ANGPTL3)." (PMID 37138899, 2022).
hypothyroidism (4 papers, 2019 to 2025). Abnormally low levels of thyroid hormone. "Furthermore, the study suggests potential therapeutic implications of ANGPTL3 inhibition for both hypothyroidism and hyperthyroidism, alongside the observed risk increase in hyperthyroidism with LPL activation." (PMID 38425755, 2024). "ANGPTL3 was found to be down-regulated by thyroid hormones in a rat model, and increased in hypothyroidism patients, the evidences which highlight the increased rate of cardiovascular diseases with thyroid dysfunctions." (PMID 39897058, 2025). "We also found suggestive evidence supporting the potential therapeutic use of ANGPTL3 inhibitors for both hypothyroidism and hyperthyroidism." (PMID 38425755, 2024). "Additionally, our study also provided suggestive evidence for the potential therapeutic use of ANGPTL3 inhibitors for both hypothyroidism and hyperthyroidism, while showing that LPL activation was related to increasing hyperthyroidism risk." (PMID 38425755, 2024). "Our data show that serum Angptl3 and 8 levels are increased in clinical and subclinical hypothyroid patients and that Angptl3 and 8 may serve as possible biomarkers of hypothyroid disease." (PMID 31380419, 2019). "Thus, it appears that thyroid insufficiency may impact on circulating Angptl3 and 8 levels." (PMID 31380419, 2019).
renal cell carcinoma (4 papers, 2021 to 2025). "ANGPTL3 tumoral expression was also upregulated in human high‐grade serous ovarian carcinoma and colorectal cancer tissues, while they showed downregulation in renal cell carcinoma." (PMID 39888285, 2025). "However, the expressing pattern and functions of ANGPTL3 renal cell carcinoma (RCC) were rarely reported." (PMID 34484467, 2021).
chronic hepatitis (3 papers, 2019 to 2025). An active inflammatory process affecting the liver for more than six months. "Another investigation showed that the serum levels of ANGPTL3 were higher in HCC patients than in those with chronic hepatitis or in healthy controls." (PMID 39708716, 2025). "ANGPTL3 expression and serum levels could act as novel biomarkers in the diagnosis of chronic hepatitis and HCC, and ANGPTL3 expression could be useful for discriminating HCC from chronic hepatitis in patients." (PMID 34671598, 2021). "Previously, circulating levels of ANGPTL3 and ANGPTL4 were found to be elevated in HCC patients compared to those with chronic hepatitis and healthy individuals." (PMID 39708716, 2025).
chronic kidney disease (3 papers, 2018 to 2023). Impairment of the renal function secondary to chronic kidney damage persisting for three or more months. "The ANGPTL3 which mainly regulates lipid metabolism in the body, is thought to be a connection point of hyperlipemia and proteinuria, which may be closely related to chronic renal disease lipid metabolism and proteinuria." (PMID 31103046, 2019).
familial combined hypolipidemia (3 papers, 2018 to 2024). "In fact, humans with complete genetic deficiency of ANGPTL3 exhibit familial combined hypolipidemia (FHBL2) and associated reductions in very low-density lipoprotein (VLDL) cholesterol, LDL, and HDL." (PMID 38219820, 2024).
generalized lipodystrophy (3 papers, 2020 to 2025). Almost complete absence of subcutaneous and/or visceral adipose tissue. "In humans, patients with generalized lipodystrophy receiving metreleptin replacement therapy exhibited a rapid decline in plasma ANGPTL3, consistent in direction with animal and cellular data and supporting negative regulation of hepatocyte ANGPTL3 by the energy/adipose-reserve–leptin axis." (PMID 41561063, 2025). "Interestingly, metreleptin has also been shown to reduce elevated ANGPTL3 levels observed in generalized lipodystrophy." (PMID 34865644, 2021). "In addition, plasmatic levels of ANGPTL3 were elevated in patients with generalized lipodystrophy and significantly reduced after metreleptin therapy." (PMID 33273510, 2020).
Hyperglycemia (3 papers, 2014 to 2022). An increased concentration of glucose in the blood. "ANGPTL3 was demonstrated as playing a key role in lipid metabolism by studies in a group of strain KK obese mice, where ANGPTL3 was associated with hyperinsulinemia and hyperglycemia." (PMID 35371605, 2022). "Serum glucose values were measured to assess the effect of anti-ANGPTL3/IL22 fusion protein treatment on hyperglycemia." (PMID 36544775, 2022).
Hyperinsulinemia (3 papers, 2018 to 2022). An increased concentration of insulin in the blood. "As to the mechanisms leading to increased circulating ANGPTL3, our and previous results hint toward a possible involvement of hyperinsulinemia." (PMID 34440242, 2021). "Another factor contributing to this effect might be severe hyperinsulinemia in diabetic subjects, as high levels of insulin were shown to reduce systemic ANGPTL3 by decreasing its liver expression." (PMID 29695708, 2018).
ischemic stroke (3 papers, 2018 to 2025). A stroke disorder caused by obstruction of blood flow to the brain, due to thrombotic (local blood clot formation) or embolic (due to a blood clot or other material traveling from another site) event. "Previously, MR methods have been used to investigate the causal relationship of circulating protein biomarkers on ischemic stroke and the impact of angiopoietin-like protein 3 (ANGPTL3) and 4 (ANGPTL4) inhibition of lipoprotein lipase (LPL) on CVD." (PMID 40904650, 2025).
lipid metabolism disorders (3 papers, 2022 to 2024). "To date, clinical studies have been carried out using ANGPTL3 inhibitors (specify what and add a reference) to improve the lipid metabolism disorders of patients in the cardiovascular field." (PMID 35399079, 2022). "These DEGs included ACSL1, ANGPTL3, and ELOVL6, suggesting the possibility of a lipid metabolism disorder in the liver of exposed T. scripta elegans." (PMID 39088466, 2024).
lipodystrophy (3 papers, 2019 to 2021). A congenital or acquired disorder characterized by abnormal loss or redistribution of the adipose tissue in the body. "Furthermore, leptin replacement therapy (metreleptin) in patients with lipodystrophy decreased significantly serum ANGPTL3 levels, total cholesterol and triglyceride concentrations." (PMID 33273510, 2020).
liver cancer (3 papers, 2023 to 2025). An epithelial or non-epithelial malignant neoplasm that arises from the liver. "In the current study, the online available dataset (GSE94550) and in vitro assays demonstrated that ANGPTL3 was downregulated in sorafenib-resistant liver cancer cell lines." (PMID 39708716, 2025). "Compared to the parental liver cancer cell lines, expression levels of ANGPTL3 were significantly decreased in sorafenib-resistant cell lines." (PMID 39708716, 2025). "Accordingly, we believed that ANGPTL3 played s tumor suppressor role in regulation of cell motility, sorafenib response and lipid peroxidation of liver cancer cells." (PMID 39708716, 2025). "Through online available dataset analysis and in vitro experiments, we uncovered that ANGPTL3 manifested lower expression in sorafenib-resistant liver cancer cell lines." (PMID 39708716, 2025). "Based on the endogenous expression levels of ANGPTL3 in liver cancer cell lines, the stable models of ANGPTL3 overexpression and knockdown in Huh7, J7, Mahlavu and Hep3B cell lines were established." (PMID 39708716, 2025). "In the current study, online available dataset analysis uncovered that angiopoietin-like protein 3 (ANGPTL3) manifested lower expression in sorafenib-resistant liver cancer cell lines." (PMID 39708716, 2025). "We found that treatment with ANGPTL3-CM in liver cancer cell lines (Mahlavu, Huh7, and HepG2) led to reduced cell migration, indicating that both intracellular and extracellular ANGPTL3 suppress cell motility." (PMID 39708716, 2025). "This is the first evidence that ANGPTL3 regulates CPT1A protein stability in sorafenib-resistant liver cancer cell lines." (PMID 39708716, 2025). "In the current study, we aimed to investigate the effects of ANGPTL3 on sorafenib response in liver cancer cell lines." (PMID 39708716, 2025). "•This study identified that ANGPTL3 manifested lower expression in sorafenib-resistant liver cancer cell lines." (PMID 39708716, 2025). "We found that mRNA levels of SNAI1 were increased in ANGPTL3-depleted liver cancer cell lines." (PMID 39708716, 2025). "The information of ANGPTL3 on sorafenib response in liver cancer cell lines was limited." (PMID 39708716, 2025). "Targeting ANGPTL3/SNAI1/CPT1A axis may serve as a therapeutic approach to improve prognosis of liver cancer patients with sorafenib resistance." (PMID 39708716, 2025). "To further confirm whether ANGPTL3 was involved in sorafenib response, we established three sorafenib-resistant liver cancer cell lines (HepG2SR, Huh7SR and J7SR)." (PMID 39708716, 2025). "ANGPTL3 expression was lower in HH compared to other liver cancer cell lines." (PMID 39708716, 2025). "Notably, overexpression of ANGPTL3 induced lipid peroxidation production of liver cancer cell lines." (PMID 39708716, 2025). "So far, the effects of ANGPTL3 on liver cancer progression and sorafenib resistance remain unclear." (PMID 39708716, 2025). "However, the functional role of ANGPTL3 in drug resistance in liver cancer remains unclear." (PMID 39708716, 2025). "Our results uncover a mechanism through which ANGPTL3 reduces SNAI1/CPT1A expression, thereby suppressing tumor metastasis and drug resistance in liver cancer." (PMID 39708716, 2025). "ANGPTL3 increases sorafenib sensitivity by inhibition of SNAI1 and CPT1A in liver cancer." (PMID 41562091, 2025).
oral cancer (3 papers, 2015 to 2023). "For instance, ANGPTL3 was found to display a high level in oral cancer and possess a potential diagnostic value according to the results of ROC assays." (PMID 34484467, 2021). "Functionally, knockdown of ANGPTL3 was shown to suppress the proliferation of oral cancer cells via activating ERK/MAPK pathway." (PMID 34484467, 2021).
oral squamous cell carcinoma (3 papers, 2015 to 2024). "Based on this evidence, we hypothesized that ANGPTL3 may be associated with development of human cancer including oral squamous cell carcinoma (OSCCs)." (PMID 25644496, 2015). "For instance, ANGPTL3 was significantly upregulated in oral squamous cell carcinoma (OSCC)‐derived cell lines compared to normal tissues." (PMID 32410376, 2020). "However, little is known about the relevance of ANGPTL3 in the behavior of oral squamous cell carcinoma (OSCC)." (PMID 25644496, 2015).
STomach ADenocarcinoma (3 papers, 2020 to 2025). "Both Cho28 (FC = −2.092) and DErrico25 (FC = −3.247) exhibited elevating transcriptional level of ANGPTL3 in mixed‐type gastric adenocarcinoma." (PMID 32410376, 2020). "In different datasets for ANGPTL3, we observed gastric adenocarcinoma having a FC = −2.074 compared with normal stomach reported by Cho,28 and a similar trend was found in Cui24 (FC = −3.703) and Wang's27 (FC = −4.953) datasets." (PMID 32410376, 2020). "METTL3 may also play a carcinogenic role in STomach ADenocarcinoma (STAD) by downregulating the expression of ANGPTL3 through an M6A-dependent mechanism." (PMID 41312360, 2025).
anorexia nervosa (2 papers, 2018 to 2021). A disorder most often seen in adolescent females characterized by a refusal to maintain a minimally normal body weight, an intense fear of gaining weight, a disturbance in body image, and, in postmenarcheal females, the development of amenorrhea. "On the contrary, in patients with anorexia nervosa re-alimentation reduces ANGPTL3 levels." (PMID 33451033, 2021).
arthrosis (2 papers, 2022 to 2025). "The strongest unfavourable association of genetically predicted ANGPTL3 inhibition was with arthrosis (OR = 1.37, 95% CI=1.23 to 1.53, p=1.1e-08)." (PMID 40052268, 2025).
breast carcinoma (2 papers, 2022 to 2023). "The present work aimed to determine plasma levels of PCSK9, ANGPTL3 and Lp(a) in women with benign disease of the breast, stage 0 and stage III breast cancers." (PMID 36203122, 2022). "Since the role, if any, of PCSK9, ANGPTL3, and Lp(a) in cancers has not been fully investigated to date, the current study aims to establish the levels of these lipid-related proteins in breast cancers." (PMID 36203122, 2022).
cervical cancer (2 papers, 2022 to 2023). A primary or metastatic malignant neoplasm involving the cervix. "Then, the effects of ANGPTL3 on cell proliferation, invasion and migration and angiogenesis in cervical cancer and αvβ3 expression were analyzed." (PMID 35038961, 2022). "Similarly, a recent study reported that ANGPTL3 depletion inhibited cervical cancer cells viability." (PMID 37344779, 2023). "In the present study, we hypothesized that ANGPTL3 may regulate cell proliferation, migration and angiogenesis in cervical cancer through binding to αvβ3." (PMID 35038961, 2022). "We first analyzed ANGPTL3 expression in various cervical cancer cell lines." (PMID 35038961, 2022). "However, whether the combination of ANGPTL3 and αvβ3 affects biological activities of cervical cancer cells is still uncertain." (PMID 35038961, 2022). "Nevertheless, whether ANGPTL3 functions in cervical cancer (CC) has not yet been reported." (PMID 35038961, 2022).
coronary artery stenosis (2 papers, 2021 to 2024). "Compared to that in the nonstenosis group, the concentration of ANGPTL3 significantly increased in all of the coronary stenosis groups (P < 0.01)." (PMID 34742313, 2021). "The plasma ANGPTL3 level was higher (51.71 ± 52.67 vs. 24.65 ± 10.32 ng/mL, P < 0.001) and that of ANGPTL4 was lower (454.66 ± 269.05 vs. 875.49 ± 961.15 ng/mL, P < 0.001) in the coronary artery stenosis ≥ 10% group than in the < 10% group." (PMID 34742313, 2021). "The plasma ANGPTL3 level was higher and that of ANGPTL4 lower in the coronary stenosis > 10% group than in the nonstenosis group." (PMID 34742313, 2021).
dermatomyositis (2 papers, 2014 to 2025). Dermatomyositis (DM) is a type of idiopathic inflammatory myopathy characterized by evocative skin lesions and symmetrical proximal muscle weakness. "ANGPTL-3 levels are elevated in patients with rheumatic disorders like dermatomyositis and systemic sclerosis." (PMID 41026696, 2025). "In addition to that, ANGPTL3 has been shown in vivo to be negatively regulated by thyroid hormone and serum ANGPTL3 levels have been reported to be significantly higher in patients with rheumatic disorders, including dermatomyositis and systemic sclerosis." (PMID 24478758, 2014).
gestational diabetes (2 papers, 2023 to 2025). Carbohydrate intolerance first diagnosed during pregnancy. "For the first time, we demonstrated that the ANGPTL3-4-8 axis appears to be dysregulated in pregnancies with gestational diabetes, both at the circulating level after ingestion and at the level of placental expression." (PMID 36768809, 2023). "The expression of ANGPTL3, ANGPTL4, and ANGPTL8 in the placenta of women with gestational diabetes has previously been shown to be positively correlated with birth weight of the offspring." (PMID 39984579, 2025). "In this study, we evaluated the response of ANGPTL3, 4, and 8 after the intake of a mixed meal in women with normal glucose tolerance and gestational diabetes, and we assessed their gene expressions in different placental locations." (PMID 36768809, 2023).
glomerular disease (2 papers, 2015 to 2023). "ANGPTL3 (angiopoietin-like 3) was responsible for angiogenesis, glycerol, fatty acid metabolic processes, cell matrix adhesion, and integrin-mediated signaling pathways, and a role for ANGPTL3 in podocyte injury and glomerular disease was shown recently." (PMID 26536600, 2015).
liver fibrosis (2 papers, 2021 to 2023). "We determined ANGPTL-3 and ANGPTL-4 levels in five groups of clinical samples ranging from the acutely infected with almost no liver fibrosis to cirrhotic patients with HCC." (PMID 34360721, 2021).
minimal change disease (2 papers, 2022 to 2023). "It has been demonstrated that ANGPTL3 level was upregulated in minimal change nephrotic syndrome (MCNS) kidney tissues." (PMID 37266537, 2023).
pancreatitis (2 papers, 2025 to 2026). Inflammation of the pancreas. "Finally, we discuss emerging RNA-targeted therapies against apolipoprotein C-III and angiopoietin-like 3, which are reshaping prevention strategies for familial and persistent chylomicronaemia and may reduce pancreatitis burden in the highest-risk phenotypes." (PMID 41745085, 2026).
polycystic ovary syndrome (2 papers, 2023 to 2026). A disorder that manifests as multiple cysts on the ovaries. "There are several lines of evidence that ANGPTL3 is associated with lipid profile and lipoprotein metabolism, ANGPTL3 indicated a positive association with TG in the Finnish population, patients with polycystic ovary syndrome preeclamptic pregnant women." (PMID 37312105, 2023).